RNY4P9 (RNY4 pseudogene 9)
Gene: Miscellaneous RNA gene on chromosome 13 (49,908,634 to 49,908,730, reverse strand). Ensembl gene ENSG00000200064.
Homologues: Orthologues: chimpanzee Y_RNA (98% identical). Paralogues in human: RNY4P29 (93% identical), RNY4P30 (90% identical), Y_RNA (89% identical), RNY4 (88% identical), RNY4P6 (88% identical), Y_RNA (88% identical), RNY4P7 (87% identical), RNY4P10 (86% identical), RNY4P13 (86% identical), RNY4P19 (86% identical), Y_RNA (86% identical), RNY4P17 (85% identical), and 90 more.